NHSL1 (NHS like 1)
Synonyms: C6orf63; KIAA1357; bA43P8.1
Tractability: No criterion of Open Targets' tractability assessment is met for any kind of drug.
Gene: Protein-coding gene on chromosome 6 (138,422,043 to 138,693,253, reverse strand). Ensembl gene ENSG00000135540.
Subcellular location (Human Protein Atlas): Nuclear membrane; Nucleoplasm
Gene Ontology:
Biological process: cell differentiation
Genetic constraint (gnomAD): Loss-of-function variants: 46 observed, 92.23 expected, observed/expected ratio (o/e) 0.5, 90% interval 0.39 to 0.64. The upper end of that interval is the gene's LOEUF score, 0.64, which puts it in group 2 of 6, group 1 being the genes least tolerant of losing a copy. Missense variants: 1,967 observed, 2,089.1 expected, observed/expected ratio (o/e) 0.94, 90% interval 0.91 to 0.98. Synonymous variants: 783 observed, 836.63 expected, observed/expected ratio (o/e) 0.94, 90% interval 0.88 to 0.99.
Homologues: Orthologues: chimpanzee NHSL1 (98% identical), macaque NHSL1 (94% identical), dog NHSL1 (79% identical), pig NHSL1 (75% identical), rat Nhsl1 (75% identical), guinea pig NHSL1 (74% identical), mouse Nhsl1 (73% identical), rabbit NHSL1 (58% identical), tropical clawed frog nhsl1 (40% identical), zebrafish nhsl1b (38% identical), zebrafish nhsl1a (35% identical). Paralogues in human: NHS (25% identical), NHSL2 (17% identical), NHSL3 (14% identical).
Diseases named in the same sentence as NHSL1 in open-access papers:
NHSL1 is named in the same sentence as 14 diseases in open-access papers, as found by Europe PMC text mining. Sharing a sentence is not in itself a finding about the gene and the disease. The quoted sentences say what the papers report.
colon cancer (2 papers, 2021). "Through lasso regression analysis, we selected seven optimal RNA construction models, namely, AGAP3, NHSL1, ENOPH1, NRG1, SNHG16, hsa-mir-1271-5p, and hsa-mir-26b-5p, to predict the prognosis of patients with colon cancer." (PMID 34692670, 2021).
melanoma (2 papers, 2021 to 2025). A malignant, usually aggressive tumor composed of atypical, neoplastic melanocytes. "Both NHSL1 antibodies detect endogenous NHSL1 as a 260 kDa protein by immunoblotting in the melanoma cell line B16-F1 and the breast epithelial cell line MCF10A." (PMID 34584076, 2021). "Very recently, two studies have identified NHSL1 as a regulator of cell migration in vitro, in the mouse melanoma cell line B16-F120 and in non-malignant human breast epithelial cells." (PMID 40021913, 2025).
Alzheimer disease (1 paper, 2024). A progressive, neurodegenerative disease characterized by loss of function and death of nerve cells in several areas of the brain leading to loss of cognitive function such as memory and language. "Four SNPs are mapped to FBLN2, ADAM 10, NHSL1, and ST3GAL1 genes previously associated with Alzheimer Disease." (PMID 38291454, 2024).
Astigmatism (1 paper, 2025). A type of refraction error associated with abnormal curvatures on the anterior and/or posterior surface of the cornea. "Further functional investigation to elucidate the role of NHSL1 variants in ocular development and astigmatism is warranted." (PMID 41320768, 2025). "The associations of NHSL1 variants with IA have not been investigated in adults, but the results suggest that NHSL1 likely influences astigmatism risk through a mechanism that begins in early life and persists over time." (PMID 41320768, 2025).
breast carcinoma (1 paper, 2025). "Further mechanistic studies are needed to elucidate the functional implications of NHSL1 in breast cancer." (PMID 40312292, 2025).
gastric cancer (1 paper, 2019). A primary or metastatic malignant neoplasm involving the stomach. "a and b Relative expression of circNHSL1 and NHSL1 mRNA was detected by qRT-PCR in gastric cancer cells after transfection of si-circNHSL1, pEX-3-circNHSL1 or negative control." (PMID 31438963, 2019). "The level of NHSL1 mRNA was low in gastric cancer tissues with metastasis." (PMID 31438963, 2019). "Combined with the results that NHSL1 expression was not changed by down-regulation or up-regulation of circNHSL1 in gastric cancer cells, circNHSL1 did not regulate NHSL1 mRNA expression through sponging miRNAs." (PMID 31438963, 2019).
hepatocellular carcinoma (1 paper, 2024). A malignant tumor that arises from hepatocytes. "The expression of pri-miR-3145 showed a strong correlation with the Nance–Horan syndrome-like 1 (NHSL1) gene, as it is encoded within an intron of NHSL1, and higher NHSL1 expression in hepatocellular carcinoma patients with HBV infection was associated with better prognosis." (PMID 39834379, 2024).
lung adenocarcinoma (1 paper, 2019). A carcinoma that arises from the lung and is characterized by the presence of malignant glandular epithelial cells. "In addition, factors previously identified to be specific markers of lung adenocarcinoma were upregulated, including PROM2, CLDN3, and TJP3, as were genes proposed to have potential diagnostic or prognostic value in human cancers, including MMP9, AGR2, SULF1, NHSL1, LGR5, MUC1, and PIK3C2G." (PMID 31434729, 2019).
Nance-Horan syndrome (1 paper, 2025). A syndrome characterized by the association in male patients of congenital cataracts with microcornea, dental anomalies and facial dysmorphism. "NHS is a known regulator of actin cytoskeletal remodelling and is involved in lens development; mutations in NHS cause the Nance-Horan syndrome, which, among other features, manifests as bilateral cataract, supporting the biological plausibility of NHSL1’s involvement in IA pathogenesis." (PMID 41320768, 2025).
viral infection (1 paper, 2024). "miR-3145-3p targets HBV; however, the role of the NHSL1 gene in viral infection remains unclear." (PMID 39834379, 2024).
cancer (4 papers, 2019 to 2025). A tumor composed of atypical neoplastic, often pleomorphic cells that invade other tissues. "Circ_NHSL1 is enriched in exosomes from cancer cells; therefore, it is feasible that exosomal circ_NHSL1 facilitates migration, invasion, and glutaminolysis in recipient cancer cells by upregulating YWHAZ expression." (PMID 35055115, 2022). "We propose that elevated NHSL1 expression in BC patients may initially reduce cancer cell migration, leading to a better early response to NAC." (PMID 40312292, 2025).
tumor (2 papers, 2024 to 2025). "NHSL1 is a tumor suppressor that negatively regulates lamellipodia stability and, thus, cell migration efficiency." (PMID 39834379, 2024).
NHSL1 also shares sentences with these, for which no sentence is quoted: adenosquamous carcinoma (1 paper); lung carcinoma (1).